S100A6 (S100 calcium binding protein A6)
Diseases named in the same sentence as S100A6 in open-access papers (continued):
Sharing a sentence is not in itself a finding about the gene and the disease.
nervous system disease (3 papers, 2019 to 2024). "Further studies on how S100A6 protein facilitates B lymphocyte infiltration and whether other factors in AE serum also contribute to this phenomenon are likely to improve our understanding of AE, and hopefully to reveal novel therapeutic targets for this emerging treatable neurological disorder." (PMID 31850060, 2019).
adenocarcinoma (2 papers, 2000 to 2004). A common cancer characterized by the presence of malignant glandular cells. "In all cases of adenocarcinoma studied, loss of expression of both S100A6 and cytokeratin 5 was seen in the malignant cells." (PMID 15280928, 2004). "The frequency of S100A6 loss we observed in our series of adenocarcinomas is comparable to the frequency of loss reported for Annexin I and II." (PMID 15280928, 2004). "In contrast to the intense expression seen in the basal cell layer of benign glands, a complete loss of S100A6 staining was seen in all 66 cases of adenocarcinomas, regardless of Gleason score." (PMID 15280928, 2004).
kidney (2 papers, 2004 to 2023). "The upregulated genes included known acute kidney injury markers such as Havcr1 (Kim1), S100a6, Clusterin, Cdkn1a, and Spp127–29." (PMID 37898693, 2023).
bacterial infection (1 paper, 2024). "S100A6 has known functions as a damage associated molecular pattern (DAMPs) during bacterial infection and modulates the inflammatory response." (PMID 38907250, 2024).
S100A6 also shares sentences with these, for which no sentence is quoted: adenomyosis (4 papers); Anxiety (4); Infertility (4); cardiovascular disease (3); leiomyoma (3); cognitive disorder (2); Impaired glucose tolerance (2); ischemia (2); liver cancer (2); Spitz nevi (2); vitamin D deficiency (2); acute pancreatitis (1); alcoholic cirrhosis (1); Allergy (1); anaplastic large cell lymphoma (1); aortic regurgitation (1); aortic stenosis (1); atopic dermatitis (1); autoimmune disease (1); autoimmune myocarditis (1); benign breast tumors (1); benign tumour (1); bladder carcinoma (1); Blindness (1); breast adenocarcinoma (1); Burkitt lymphoma (1); cardiomyopathies (1); colon adenocarcinoma (1); colorectal adenoma (1); coronary heart disease (1).
A further 51 diseases each share a sentence with S100A6 in 1 paper.